TNF (tumor necrosis factor)
Diseases named in the same sentence as TNF in open-access papers (continued):
Sharing a sentence is not in itself a finding about the gene and the disease.
infection (continued). "In vitro experiments showed that siTIPE2 infection exacerbated the increased TNF-α and IL-6 concentrations, while Ad-TIPE2 infection reversed the increased TNF-α concentration in differentiated THP-1 cells under high glucose conditions (50 mmol/L)." (PMID 28626770, 2017). "In contrast, the IL-6 and TNF-α mRNA and protein levels following P. gingivalis infection were significantly reduced by the oral administration of LG2055 before infection." (PMID 28373699, 2017). "The results showed that compared to others the changes of TNF-, Il-12, IL-5, and GM-CFS were significant, and the level of these cytokines in serum increased on week 5 after infection, peaked on week 6, and then began to decrease." (PMID 28539607, 2017). "RIP1 plays a key role in NF-κB signaling after TNFα treatment and HCMV inhibits NF-κB activation in the late stages of infection." (PMID 28570668, 2017). "MCs also produce a wide variety of soluble mediators potentially relevant to mycobacterial immunity, including IL-13, IL-12, IL-6, IL-4, TNF-α, CCL5, CXCL2, CCL7, and CCL2, following infection with Streptococcus equi." (PMID 29089945, 2017). "After 6 h of infection, we found significantly decreased levels of pro-inflammatory cytokines, including IL-1β, IL-6, IL-12, IFN-β, and TNF-α induced by MAP 0908 in BMDM at both translational and transcriptional levels." (PMID 29375563, 2017). "In the persistent-infection status, cytokine production was delayed and was composed of a high ratio of proinflammatory versus anti-inflammatory cytokines, such as IL-6, IFN-γ, TNF-α, and IL-10." (PMID 27799331, 2017). "Analysis of cytokines production by spleen and MLN cells in mice model have shown the production of IL-4, IL-10, IL-13, IL-17, IL-22, TNF-α, and IFN-γ after infection with both WB and GS strains." (PMID 28979269, 2017). "The notable findings in the present study were the early peak in both IL-6 and TNF-α levels, the high inflammatory cell infiltration in BAL fluids, and the severe pulmonary inflammation at 3 days post-infection in asthmatic/A(H1N1)pdm09 mice." (PMID 28831046, 2017). "The resulting data indicate that older children respond with diminished levels of the pro-inflammatory cytokines TNF, IL2 and IL6, as well as Th1-biased chemokines when compared to younger children at the same stage of infection." (PMID 29284469, 2017). "Similar results were obtained by treating cells with the MLCK inhibitor, ML7, demonstrating a role for MLCK in TNF-α-, TNF-β-, TWEAK- and LIGHT-dependent HCVpp infection of polarized to HepG2." (PMID 27983476, 2017). "Most inflammatory markers, such as interleukin-6 (IL-6), tumor necrosis factor-α (TNF-α), CRP, and fibrinogen, increased significantly in response to infection and in active diseases states." (PMID 28539965, 2017). "A gate on CD11b+ F4/80+ myeloid cell population showed that naïve TNF KO and tmTNF KI mice presented similar cell numbers compared to WT mice, but BCG infection induced a 6-fold increase at day 14 post-infection in all groups of mice." (PMID 28890718, 2017). "In conclusion, the present results suggest that increases in TNFα signaling, likely through the TNFR1 pathway, contribute to hyperexcitability and the increased probability of seizures in the hippocampus after TMEV infection." (PMID 28497109, 2017). "Plasma levels of tumor necrosis factor (TNF)-α and interferon (IFN)-γ however were significantly increased in mice with a disrupted gut microbiota, 72 hours after infection." (PMID 28422970, 2017). "Piglets vaccinated with the avirulent strain, 05HAS68, had increased TNF-α and IFN-γ levels in the peripheral blood and were fully protected from challenge infection with the most virulent S. suis 2 strain, 05ZYH33." (PMID 28292261, 2017). "PBMC infection with EHV-2 also increased mRNA expression of IFN-β, IFN-γ, and TNF-α, as observed after α-EHV infection." (PMID 28925977, 2017).
infection (continued). "The pro-inflammatory mediators (TNF and IL-6) MHC-I/II and B7.2 (CD86) were also up-regulated during infection over time." (PMID 28067803, 2017). "Compared with PBS controls, sublethal infection also markedly induced mRNA levels of TLR2, IFN-γ, TNF-α, CXCL9, CXCR3, and Ang2." (PMID 28742087, 2017). "As observed in the CLEC5A− human M-Mφ, reduced levels of TNF-α and IP-10 (P = 0.063 and P = 0.046, respectively) were detected in BMM of CLEC5A−/− mice compared to those in the WT mice after infection." (PMID 27795434, 2017). "The expression of MAPK family genes, dual specificity phosphatases (DUSP) family members, TNF, IL-1, IL-6, JUN and NF-κB family genes were upregulated at early stage of infection in all the tissues indicated triggering of MAPK pathway." (PMID 28704394, 2017). "siTIPE2 infection exacerbated the increased TNF-α and IL-6 concentrations in differentiated THP-1 cells under high glucose conditions (50 mmol/L), while infection with TIPE2 adenovirus reversed the increased TNF-α concentration." (PMID 28626770, 2017). "PBMC infection with EHV-4 induced an increased mRNA expression of IFN-α, IFN-β, IFN-γ, and TNF-α, similar to the response observed after EHV-1 infection." (PMID 28925977, 2017). "The increase in TNFα and IFNγ mRNA in the neonatal lungs after MRSA infection demonstrate that neonates are capable of inducing a pro-inflammatory response following infection." (PMID 28060871, 2017). "Comparison of common genes involved in KEGG pathways at early and late stages of infection across different tissues also showed enrichment of Toll—like receptor, NF-κB, MAPK, TNF, JAK-STAT and NOD like receptor signaling pathways." (PMID 28704394, 2017). "IFN-γ R−/− Hoxb8 neutrophils showed an unimpaired chemokine and cytokine response upon infection but were unable to produce significant amounts of RANTES and TNF after IFN-γ stimulation." (PMID 28697801, 2017). "We found that the levels of IL-1α, INF-γ, TNF-α, MCP-1, IL-1β, IL-10, IL-6, IL-27, and IL-17α in the lungs post infection were significantly different between alcohol- and pair-fed mice." (PMID 28604843, 2017). "The infection also activated signal transduction pathways including MAPK, NF-κB, JAK-STAT, NOD and TNF signaling." (PMID 28704394, 2017). "The results showed that the mRNAs of IP-10, TNF-α, IL-8, MIP-1α, IFN- α, and MIG were significantly reduced in fr 14-treated cells at 24 h post infection." (PMID 28061784, 2017). "In fact, some studies showed that TLR2-defective mice infected with C. albicans are less resistant to infection, due to their inability to release TNF-α and MIP-2 or TNF-α, IL-12 and IFN-γ." (PMID 28344593, 2017). "The secretion of inflammatory cytokines TNF-α, IL-1β, IL-6 and IFN-γ were induced in human PBMC from 1 day after infection." (PMID 27489303, 2016). "When compared with the chicken H7N9-CK, the human H7N9-HU induced a stronger TNF-α response at 12 and 24 h post-infection, but a weaker IFNL1 response between 12 and 48 h post-infection." (PMID 26975414, 2016). "As expected, following infection with IAV, pulmonary concentrations of IL-1β, TNF-α, IFN-γ, and IL-12p70 were significantly increased during the first week of infection in all females, regardless of P4 treatment (P<0.05)." (PMID 27631986, 2016). "Other inflammatory mediators such as interleukin (IL)-1β, IL-6, tumor necrosis factor (TNF)-α, and IL-8, have also been found to be elevated in response to the infection." (PMID 28702296, 2016). "In contrast to the unchanged TNFα mRNA levels, a decrease in IFNB1 mRNA was observed, which correlates with the reduced SNRNP200 mRNA at 1 hour post-infection in MDM." (PMID 27454487, 2016). "On counter with such antigens, the complex interaction of antigen presenting cells, T cells and inflammatory mediators like IL1α, IL1β, TNFα, IL12, IL18 and IL23 lead to proinflammatory immune response and further clearance of infection." (PMID 27301453, 2016).
infection (continued). "Three days post infection, sham + IAV + vehicle mice had increased mRNA expression of pro-inflammatory chemokines (CCL-2, CXCL-2, CXCL-10), cytokines (GM-CSF, TNF-α, IL-1β, IL-6) and proteases (MMP-12) compared to sham + diluent + vehicle mice." (PMID 26877172, 2016). "Topical application of BC-DETC significantly decreased lesion size, parasite load and the inflammatory response at the infection site, as well as the production of both IFN-γ and TNF." (PMID 27922065, 2016). "Our results show up-regulated expression of cytokines including TNF-α, IL-6 and IL-10 in 2%DMSO-treated DENV-infected mice and SB203580 treatment significantly reduced the TNF-α, IL-6 and IL-10 expression upon DENV-infection." (PMID 26901653, 2016). "Infection with EBOV/VP35m infection resulted in a significant increase, as compared to wt EBOV, in proliferating CD4+ cells secreting IFNγ, TNFα and IL-2." (PMID 27930745, 2016). "The transcriptional levels of IL-6, TNF-a, IL-1β and MCP-1 were remarkably increased in the early stage of infection (within 12 h) and gradually decreased to their basal levels by 24 hpi." (PMID 27995095, 2016). "Processes related to cytoskeletal remodeling and cellular junctions, as well as inflammatory responses (IL-2, IL-5, IL-18, CCL2, TNF, IFN, and TGF-β signaling) were also upregulated following infection with C. concisus BAA-1457." (PMID 27677841, 2016). "The O175A and O265B reassortant viruses produced similar secretome profiles, and in both of these samples the levels of proinflammatory mediators TNF-α, CCL3, and CCL5 were lower than those resulting from WT PR8 infection." (PMID 27489273, 2016). "We found that it effectively antagonised IAPs in hepatocytes and it promoted TNF-dependent elimination of HBV and cured infection in preclinical models." (PMID 27551508, 2016). "During early infection (2wk), expression of pro-inflammatory cytokines IFN-γ, TNF-α, IL-17, IL-18, IL-22 (Th1 and Th17 responses) was negatively correlated with ANXA1 expression." (PMID 27484833, 2016). "Levels of IL-1β and TNF- α, in the sera of mice infected with all MTB strains and treated with G1-4A, started increasing at 15 days post infection, peaked to maximum at 30 days and later declined on 60 days post infection." (PMID 27148868, 2016). "Quantitative reverse transcription-PCR data showed that 30 min post PAO1 infection, transcriptions of all tested NF-κB-dependent genes, including IL-1α, IL-1β, IL-6, IFN-γ, MCP-2, MIP1α, TNF-α and TLR2, were significantly increased in Lyn-silenced MH-S cells." (PMID 29263906, 2016). "Seven days post infection, CS + IAV mice had increased mRNA expression of pro-inflammatory chemokines (CCL-2, CXCL-2), cytokines (GM-CSF, TNF-α, IL-1β, IL-6) and proteases (MMP-12) compared to sham + IAV + diluent mice." (PMID 26877172, 2016). "In contrast, 6 h after infection, markedly higher serum levels of CXCL1, TNFα, and IL-6 were detected in mice infected with biofilm-released cells than in the biofilm cell-infected counterparts." (PMID 27729907, 2016). "On day 250 post‐infection, the expression levels of IFN‐γ and TNF in the lungs of IL‐17A KO mice were significantly lower than those of wild‐type C57BL/6 mice." (PMID 27980775, 2016). "The relative levels of TNF-α, IL-1β, and MMP-9 mRNA transcripts and proteins in the hearts of mice with LCME infection were significantly higher than that in the PBS-injected controls (P < 0.05 for all at all time points)." (PMID 27800490, 2016). "IL-6, TNF-a, and MCP-1 levels induced by WT strain were obviously higher than ΔVirD4 strain infection at 12 hpi." (PMID 27995095, 2016). "In this model infection EHEC and mainly EPEC induced the lowest levels of IL-8 and TNF-α secretion compared to the other pathotypes, which correlated with the inhibitory effects on NF-κB and ERK1/2 activation." (PMID 27774437, 2016).
infection (continued). "On day 8 after infection, the total number of effector T cells and polyfunctional IFN-γ and TNF-α producing CD8 T cells were three- to fivefold reduced in CD4Cre/R-DTA mice as compared to controls." (PMID 28066432, 2016). "This revealed 13 mediators of inflammation that correlated with infection status, which were, in order of strength of significance, IL-4, IL-5, IL-7, IL-15, IFN-α, IL-12, IFN-γ, IL-17, IL-1Ra, TNF-α, IL-1β, IL-10, and IL-2." (PMID 27418744, 2016). "Here we found higher levels of p75TNFR and lower levels of bioactive TNF in the bronchoalveolar lavage (BAL) fluid of p55ΔNS mice compared to WT mice at both day 3 and day 6 post-infection that corroborates our previous findings." (PMID 27995986, 2016). "TLR7/9-/- mice produce increased levels of IL6, TNF-α, and IL17A during Histoplasma infection, and similar results have been observed for the endemic fungal pathogen P. brasiliensis during infection of TLR9-/- mice." (PMID 27459510, 2016). "In this work we evaluated IFN-γ, TNF-α, IL-10, and TGF-β mRNA expression using real-time RT-PCR in 5 target tissues at 6 months and 16 months post-infection (PI) in a canine experimental model which mimics many aspects of human VL." (PMID 27171409, 2016). "Seven days post infection, CS + IAV mice had increased mRNA expression of pro-inflammatory chemokines (CCL-2, CXCL-2, CXCL-9, CXCL-10), cytokines (GM-CSF, TNF-α, IL-1β, IL-6) and proteases (MMP-12) compared to sham + IAV + diluent mice or CS + diluent mice." (PMID 26877172, 2016). "Anti-TNF-α agents and/or anti-HMGB-1 agents improved survival rates when administered at a later stage of infection, and it became clear that efficacy was dependent on time of administration." (PMID 27556404, 2016). "Although inconsistently reported, unusually prolonged, severe, and life-threatening infections with common bacterial pathogens are being seen in children with JIA treated with combined DMARDs, including anti–TNF-α agents." (PMID 27648582, 2016). "Early after infection, many of the ESAT6-specific CD4+ T cells were polyfunctional based on their production of IL-2, IFNγ, and TNF." (PMID 26967901, 2016). "H5N1 induced significantly higher levels of TNF-α, IL-6, IL-8, IL-10 and MCP-1 than those of H7N9 viruses at 48 h post-infection." (PMID 26975414, 2016). "The classically activated macrophages produce high levels of proinflammatory cytokines such as tumor necrosis factor-α (TNF-α), interleukin-1β (IL-1β), IL-6, and reactive oxygen to protect host against the infection." (PMID 27322250, 2016). "The expression of genes encoding other cytokines were also significantly increased during infection, including the pro-inflammatory cytokines IL1, IL8, tumor necrosis factor alfa (TNF-α), interferon gamma (IFN-γ), and CSF2." (PMID 27982111, 2016). "In contrast to the release of pro-inflammatory cytokines TNFα, IL-1β and IL-6, the release of FKN increased from 24 h up to 72 h post infection." (PMID 26739172, 2016). "We also observed oscillations in levels of cytokine mediators TNF-α and HMGB-1 as the infection was resolved." (PMID 27556404, 2016). "As previously detected in naturally infected cattle, experimental infection-elicited polyfunctional responses biased toward IFN-γ/TNF-α and IFN-γ/TNF-α/IL-2 profiles." (PMID 27799930, 2016). "In our study, we evaluated cytokines produced in both the acute (IL-1α/β and TNF-α) and the chronic phases (IFN-γ, IL-10, and IL-6) of inflammation/infection and involved in the bone remodeling (IL-6)." (PMID 27478310, 2016). "The characteristic CD4 Th1 profile observed after systemic immunization was maintained after infection by lung-infiltrating antigen-specific CD4+ T cells that expressed IFN-γ and TNF-α, alone or in combination." (PMID 27525409, 2016). "The phosphorylated p65 levels increased with the infection time beyond 100%, suggesting a synergistic effect between HB101 and TNF-α induction." (PMID 27774437, 2016).
infection (continued). "In this study, total spleen cells were shown to secrete TNF-α, IFN-γ, IL-6, IL-10, CCL3, and CXCL9, suggesting an activation of splenic cells during the infection and a polarization towards a Th1 response." (PMID 27905502, 2016). "In contrast, in the head kidney, three days after infection both, IGF-I and TNF-α were lowered, IGF-I to 0.093-fold (p = 0.0001), and TNF-α to 0.079-fold (p = 0.0001), respectively." (PMID 26821056, 2016). "In TNFα-treated and HIV-1-infected 293-reporter cells, we observed NFKB activation by Vpr only at the very late time points of infection." (PMID 27383627, 2016). "Tumor necrosis factor-α (TNF-α), an inflammatory cytokine, is one such factor that increases after ischemic injury; it is also secreted in response to inflammation, infection, and trauma." (PMID 27259948, 2016). "Three days post infection, CS + IAV mice had increased mRNA expression of pro-inflammatory chemokines (CCL-2, CXCL-2), cytokines (GM-CSF, TNF-α, IL-1β, IL-6) and proteases (MMP-12) compared to sham + IAV + diluent mice." (PMID 26877172, 2016). "When compared with H7N9-CK or H7N9-HU, H5N1 induced significantly higher levels of IL-8 at 12 h post-infection; IL-8, IL-6, IL-10 and MCP-1 at 24 h post-infection; and IL-8, IL-6, IL-10, MCP-1 and TNF-α at 48 h post-infection." (PMID 26975414, 2016). "Intracellular cytokine staining paralleled these findings as infection of DCs with EBOV significantly reduced percentages of T cells positive for activation markers IFNγ, IL2 or TNFα, as well as for the marker of degranulation CD107α+." (PMID 27930745, 2016). "Classically activated macrophages (M1) develop during the early stage of infection in the presence of type I cytokine environment (IFN-γ and TNF)." (PMID 27242788, 2016). "MAIT cells were readily and specifically activated in response to DENV-treated APCs (multiplicity of infection (MOI)=1), as indicated by production of IFN-γ and Granzyme B, as well as, expression of CD38, with minimal production of TNF-α." (PMID 27337592, 2016). "The serum levels of interleukin 6 (IL-6), tumor necrosis factor-α (TNF-α), and interleukin 12p70 (IL-12p70) from the three mouse groups showed a sharp peak at 8 h after infection; the peak values returned to basal levels at 12 or 16 h after infection." (PMID 27270879, 2016). "IFN-γ secreted by CD4+ Th1 cells synergises with TNF-a to activate macrophageleishmanicidal activity.Thus, IFN-γ plays a critical role in the control of the infection." (PMID 27759762, 2016). "In the spleen, we observed a stimulatory effect of infection with Yersinia on both, IGF-I and TNF-α gene expressions with a dose-dependent increase in the E2-treated groups." (PMID 26821056, 2016). "In general, the early stage of infection is characterized by an elevation in pro-inflammatory cytokines (IFN-γ and TNF-α) with a switch to a counter-inflammatory response in late stage infection." (PMID 26807135, 2016). "Untreated and TNFα-treated (10 ng/mL) HUVEC were infected with ANDV, HTNV, PHV, or mock-infected and total RNA was collected at 12, 24, and 72 h post infection (PI)." (PMID 27486439, 2016). "TLR4 activation by M. tuberculosis was found to result in the expression of host-protective factors (e.g., TNF, IFN-γ, and NOS2) and to limit bacterial growth during in vivo infection." (PMID 27849167, 2016). "BAL fluid levels of IFN-α, IFN-γ, TNF-α, IL-6, MCP-1 and MIP-2 increased following infection, with levels of IFN-γ and MCP-1 being significantly higher in Ctsl-/- mice than in Ctsl+/+ mice (at days 7 and 14, respectively)." (PMID 27716790, 2016). "<0.01 or P<0.05) between the three infection groups and the control group with the exception of the IFN-γ and IL-6 levels in the spleen between the Sp-only and PBS group and the TNF-α levels of the lung between the CIV-only or CIV/Sp group and the PBS group." (PMID 27259293, 2016). "The absence of either TLR2 or TLR4 significantly reduced the production of TNFα and IL6 after 24 and 48 h of infection." (PMID 28119856, 2016).